IBTK (inhibitor of Bruton tyrosine kinase)
Description:
Acts as an inhibitor of BTK tyrosine kinase activity, thereby playing a role in B-cell development. Down-regulates BTK kinase activity, leading to interference with BTK-mediated calcium mobilization and NF-kappa-B-driven transcription.
Synonyms: BTKI; DKFZP564B116; BTBD26
Tractability: Antibody: UniProt places it where antibodies can reach, with medium confidence. PROTAC: ubiquitination databases record sites on it; its protein half-life has been measured.
Gene: Protein-coding gene on chromosome 6 (82,169,984 to 82,247,775, reverse strand). Ensembl gene ENSG00000005700.
Subcellular location: Cytoplasm; Membrane; Nucleus (Isoform 2)
Subcellular location (Human Protein Atlas): Nucleoplasm; Cytosol
Gene Ontology:
Molecular function: protein kinase binding; protein tyrosine kinase inhibitor activity
Biological process: negative regulation of protein phosphorylation; release of sequestered calcium ion into cytosol
Cellular component: cytoplasm; cytosol; nucleoplasm; membrane; nucleus
Genetic constraint (gnomAD): Loss-of-function variants: 30 observed, 65.05 expected, observed/expected ratio (o/e) 0.46, 90% interval 0.34 to 0.63. The upper end of that interval is the gene's LOEUF score, 0.63, which puts it in group 2 of 6, group 1 being the genes least tolerant of losing a copy. Missense variants: 759 observed, 914.78 expected, observed/expected ratio (o/e) 0.83, 90% interval 0.78 to 0.88. Synonymous variants: 285 observed, 309.88 expected, observed/expected ratio (o/e) 0.92, 90% interval 0.83 to 1.01.
Homologues: Orthologues: chimpanzee IBTK (99% identical), macaque IBTK (98% identical), dog IBTK (91% identical), rabbit IBTK (91% identical), pig IBTK (91% identical), rat Ibtk (86% identical), mouse Ibtk (86% identical), guinea pig IBTK (82% identical), tropical clawed frog ibtk (64% identical), zebrafish ibtk (56% identical), Drosophila melanogaster CG8060 (24% identical).
Diseases named in the same sentence as IBTK in open-access papers:
IBTK is named in the same sentence as 52 diseases in open-access papers, as found by Europe PMC text mining. Sharing a sentence is not in itself a finding about the gene and the disease. The quoted sentences say what the papers report.
chronic lymphocytic leukemia (16 papers, 2019 to 2026). "The expression of IBTK was significantly increased in chronic lymphocytic leukemia (CLL) progression, but decreased in remission following chemotherapy." (PMID 38738857, 2024). "Further, the expression of IBTK gene progressively increases from indolent to aggressive stage of chronic lymphocytic leukemia and decreases in disease remission after therapy." (PMID 30975981, 2019). "In chronic lymphocytic leukemia (CLL), the overexpression of IBTK has been correlated with disease progression and proved essential for B cell survival under stress induced by chemotherapeutic agents." (PMID 38371626, 2024). "One study comparedde novoand recall immune responses between patients with chronic lymphocytic leukemia (CLL) who were treated with Bruton’s tyrosine kinase (IBTK) inhibitors and patients who were never treated with these inhibitors." (PMID 36946824, 2023).
B-cell lymphomas (8 papers, 2020 to 2025). "Previous studies showed that IBTK is a potential transcriptional target of MYC in aggressive MYC-driven B cell lymphomas." (PMID 38371626, 2024). "Previously, our research has demonstrated that IBTK haploinsufficiency also influences the tumor microenvironment in a mouse model of MYC-driven B-cell lymphoma." (PMID 38371626, 2024). "Here, for the first time, we aimed at evaluating the effect of IBTK on MYC in aggressive lymphoma B cells to elucidate the role of IBTK in B-cell lymphoma progression." (PMID 35216159, 2022). "In the present study, the IBTK haploinsufficiency alters tumor development and, consequently, the tumor microenvironment by enhancing tumor vascularization in Myc-driven B cell lymphoma." (PMID 32019112, 2020). "IBTK haploinsufficiency induces enlargement of the spleen and lymph nodes, together with an increased rate of pre-B cell lymphoma." (PMID 32019112, 2020). "Differently from previous studies that have shown IBTK as a potential transcriptional target of MYC in MYC-driven B-cell lymphomas, in this study, we raised the hypothesis of an upstream effect exerted by IBtkα in regulating the expression of MYC gene." (PMID 35216159, 2022).
lymphoma (8 papers, 2018 to 2025). A malignant (clonal) proliferation of B- lymphocytes or T- lymphocytes which involves the lymph nodes, bone marrow and/or extranodal sites. "As IBTK silencing demonstrated inhibitory effects on B-lymphoma growth in vitro, we sought to investigate whether the loss of IBTK could exert anti-tumor effects in the treatment of lymphomas in an in vivo setting." (PMID 38371626, 2024). "We have also described the presence of LoF variants in the genes CR1, IBTK, and NCOR2 that have been related to B cell development and activation, agammaglobulinemia, and lymphoma, respectively." (PMID 29867916, 2018). "Allelic loss of IBTK promotes the expression of pro-angiogenic and inflammatory cytokines as VEGF family proteins together with the recruitment of tumor-associated macrophages (TAMs) as immune cells in Myc-driven lymphoma." (PMID 32019112, 2020). "Furthermore, we leveraged the transplantability of Eμ-myc lymphomas to investigate whether the inhibition of IBTK could elicit anti-tumor effects in the treatment of lymphomas in vivo." (PMID 38371626, 2024). "Altogether, these data suggest that IBTK haploinsufficiency contributes to upregulating VEGF expression and, consequently, promoting vessel growth in Myc-dependent lymphoma." (PMID 32019112, 2020).
diffuse large B-cell lymphoma (3 papers, 2016 to 2023). "In addition, deletions of the IBTK gene have been reported in relapsed diffuse large B-cell lymphoma (DLBCL), the most common subtype of non-Hodgkin lymphoma in adults." (PMID 27827994, 2016).
lymphoproliferative disorders (3 papers, 2015 to 2025). "The human inhibitor of Bruton's tyrosine kinase isoform α (IBtkα) is a BTB protein encoded by the IBTK gene, which maps to chromosomal locus 6q14.1, a mutational hot spot in lymphoproliferative disorders." (PMID 25882842, 2015). "The human inhibitor of Bruton's tyrosine kinase (IBTK) gene maps at the 6q14.1 cytogenetic location, which is a region of recurrent chromosomal aberrations in lymphoproliferative disorders." (PMID 25882842, 2015).
non-Hodgkin lymphoma (3 papers, 2020 to 2025). Distinct from Hodgkin lymphoma both morphologically and biologically, non-Hodgkin lymphoma (NHL) is characterized by the absence of Reed-Sternberg cells, can occur at any age, and usually presents as a localized or generalized lymphadenopathy associated with fever and weight loss. "In addition, we found that IBTK loss and Rituximab treatment act synergistically in reducing tumor volume and weight in the Eμ-myc mouse model of non-Hodgkin’s lymphoma (NHL)." (PMID 38371626, 2024). "In this study, we analyzed the effect of IBTK haploinsufficiency in B-lymphoma by taking advantage of Eμ-myc transgenic mice, a preclinical model of non-Hodgkin’s lymphoma." (PMID 32019112, 2020).
cervical cancer (2 papers, 2019 to 2024). A primary or metastatic malignant neoplasm involving the cervix. "In light of these findings, we sought to evaluate the pathological significance of IBTK expression in cervical cancer." (PMID 38738857, 2024). "Overexpression of inhibitor of Bruton's tyrosine kinase (IBTK) correlates with poor survival in cervical cancer." (PMID 38738857, 2024). "Consistent with this notion, we proceeded to analyze whether IBTK could regulate apoptosis in HeLa cell line (cervix cancer cells)." (PMID 30975981, 2019). "The Cancer Genome Atlas (TCGA) dataset revealed that higher IBTK mRNA expression levels were correlated with poor survival in cervical squamous cell carcinoma (CESC), which is the most prevalent histological subtype of cervical cancer." (PMID 38738857, 2024).
colorectal cancer (2 papers, 2015 to 2019). A primary or metastatic malignant neoplasm that affects the colon or rectum. "Our findings are also consistent with pro-survival activity of the human IBTK gene in colorectal cancer cells Ras-dependent signaling." (PMID 30975981, 2019). "Moreover, a genome-wide RNAi screen identified IBTK as an essential function for viability of K-Ras mutant colorectal cancer cells, supporting a role of the IBTK gene in Ras-dependent pathways." (PMID 25882842, 2015).
colon adenocarcinoma (1 paper, 2024). "Similar results were observed in IBTK-KO H1299 cells and IBTK-KD CT26 cells (murine colon adenocarcinoma)." (PMID 38738857, 2024).
gastric cancer (1 paper, 2014). A primary or metastatic malignant neoplasm involving the stomach. "From our analysis of the gastric cancer data set, the inhibitor of Bruton's tyrosine kinase (IBTK) resulted as the gene with the largest loss in connectivity." (PMID 24489837, 2014). "Since it is well established that NF-kB and Wnt/catenin signalling pathways are activated in most of gastric cancers, it is possible to guess an involvement of IBTK in the evolution of tumor." (PMID 24489837, 2014).
tumor (23 papers, 2014 to 2025). "Moving from our promising in vitro results to an in vivo setting, we utilized a preclinical mouse model of NHL to investigate the potential anti-tumor effects of IBTK loss." (PMID 38371626, 2024). "In the context of MYC-driven lymphomagenesis, the loss of IBTK primarily induces B-cell apoptosis and delays tumor onset." (PMID 38371626, 2024). "To further investigate the effects of IBTK in tumor growth in the presence of a functional immune system, we utilized a CT26 xenograft tumor model and found that immunocompetent mice implanted with IBTK-KD CT26 cells exhibited reduced tumor growth in vivo." (PMID 38738857, 2024). "In contrast, among the genes that are under-expressed, IBTK inhibits the survival and proliferation of tumor cells by influencing the tumor microenvironment." (PMID 35517862, 2022). "Taken together, these results suggest the potential involvement of IBTK in both enhanced tumor angiogenesis and TAM infiltration within the tumor." (PMID 32019112, 2020). "In summary, these results indicate that IBTK haploinsufficiency promotes Myc tumor development by modifying the tumor microenvironment." (PMID 32019112, 2020). "Our results also indicate that IBTK may play a role in tumor immune escape through modulating the eIF4F-STAT1-IRF1-PD-L1 axis." (PMID 38738857, 2024). "The tumor-suppressive effects of IBTK depletion in HeLa cells were also observed." (PMID 38738857, 2024). "Our data suggests that IBTK silencing may serve as an effective anti-tumor agent for aggressive B-Lymphomas, underscoring its role in promoting apoptosis when used in combination with Rituximab, both in in vitro and in vivo settings." (PMID 38371626, 2024). "Mounting evidence supports a novel role for IBTK in cell survival and tumor growth." (PMID 38371626, 2024). "Based on our observations in Ibtk+/- Eμ-myc mice, IBTK could represent a novel modifier gene of the tumor microenvironment, acting through the deregulation of angiogenic and inflammatory factors." (PMID 32019112, 2020). "The human IBTK gene is involved in the stress response and tumor growth." (PMID 32019112, 2020). "Increasing evidence supports the involvement of IBTK in cell survival and tumor growth." (PMID 30975981, 2019). "Our findings could be relevant for the development of IBTK inhibitors sensitizing tumor cells to apoptosis." (PMID 30975981, 2019). "Collectively, these data indicate that IBTK promotes IFN-γ-inducible PD-L1 expression and tumor immune escape." (PMID 38738857, 2024). "As IBTK-KO cells showed compromised eIF4F-initiated translation activity and downregulated STAT1 protein levels, we investigated the potential impacts of IBTK on IFN-γ-induced PD-L1 expression and tumor immune escape." (PMID 38738857, 2024). "The heatmap showed that 12 tumor suppressors formed into two clusters: cluster 1 contains seven downregulated tumor suppressors including PTEN, PSME1, DNAJB1, HSPH1, DEDD2, PAK1IP1, and MIR1244-3; and cluster 2 contains five upregulated tumor suppressors (OSGIN1, IFI27L1, MTCH2, NKD2, and IBTK)." (PMID 34571936, 2021).
cancer (10 papers, 2018 to 2025). A tumor composed of atypical neoplastic, often pleomorphic cells that invade other tissues. "Inhibitor of Bruton's tyrosine kinase (IBTK) deficiency reduces eIF4A1-dependent oncoprotein expression and neoplastic phenotypes in cancer cells." (PMID 38738857, 2024). "Collectively, these data indicate that IBTK plays critical roles in promoting oncogene expression and cancer cell malignancy by upregulating eIF4A1 activity." (PMID 38738857, 2024). "Collectively, these data indicate that mTORC1/S6K1-mediated IBTK phosphorylation favors sustained oncogenic translation and cancer cell malignancy." (PMID 38738857, 2024). "The downstream targets and biological processes of the CRL3IBTK complex are still poorly understood, but a limited number of studies suggest that IBTK plays a pro-survival role in cancer cells." (PMID 38738857, 2024). "Given the crucial role of eIF4A1 in cancer biology, we conducted additional investigations to determine if IBTK promotes neoplastic phenotypes in cancer cells." (PMID 38738857, 2024). "An increasing body of evidence highlights a novel role for IBTK in tumorigenesis and cancer growth." (PMID 38371626, 2024). "In several cancers, IBTK functions to sustain tumorigenesis and cell survival." (PMID 37066112, 2022). "Additionally, our study shows that IBTK overexpression suppresses AS-induced SG assembly and that ablation of IBTK sensitizes cancer cells to eIF4A inhibitor-induced cell death, making IBTK a potential therapeutic target to overcome intrinsic resistance to eIF4A inhibitors." (PMID 38738857, 2024). "Moreover, CRISPR/Cas9-mediated KO or shRNA-mediated KD of IBTK in multiple cancer cell lines did not alter the levels of eIF4A1/2/3." (PMID 38738857, 2024).
IBTK also shares sentences with these, for which no sentence is quoted: mantle cell lymphoma (14 papers); Hypertension (7); infection (6); autoimmune disease (5); atrial fibrillation (4); hematological malignancies (4); lupus (4); COVID-19 (3); endothelial dysfunction (3); multiple sclerosis (3); rheumatoid arthritis (3); Arrhythmia (2); cardiac arrhythmia (2); cardiovascular disease (2); follicular lymphoma (2); leukemia (2); Waldenström macroglobulinemia (2); agammaglobulinemia (1); angiosarcoma (1); aspergillosis (1); atherosclerosis (1); autoimmune disorders (1); B-cell neoplasm (1); blood cancers (1); breast carcinoma (1); cervical squamous cell carcinoma (1); chronic GVHD (1); eosinophilia (1); experimental autoimmune encephalomyelitis (1); gastric lymphoma (1).
A further 10 diseases each share a sentence with IBTK in 1 paper.